KRTAP5-6 (keratin associated protein 5-6)
Description:
In the hair cortex, hair keratin intermediate filaments are embedded in an interfilamentous matrix, consisting of hair keratin-associated protein (KRTAP), which are essential for the formation of a rigid and resistant hair shaft through their extensive disulfide bond cross-linking with abundant cysteine residues of hair keratins. The matrix proteins include the high-sulfur and high-glycine-tyrosine keratins.
Synonyms: KRTAP5.6
Tractability: No criterion of Open Targets' tractability assessment is met for any kind of drug.
Gene: Protein-coding gene on chromosome 11 (1,697,195 to 1,697,755, forward strand). Ensembl gene ENSG00000205864.
Pathways (Reactome):
Developmental Biology: Keratinization
Gene Ontology:
Molecular function: protein binding
Cellular component: cytosol
Genetic constraint (gnomAD): Loss-of-function variants: 3 observed, 3.77 expected, observed/expected ratio (o/e) 0.8, 90% interval 0.35 to 1.75. That is too few expected variants to judge how well the gene tolerates losing a copy. Missense variants: 175 observed, 163.25 expected, observed/expected ratio (o/e) 1.07, 90% interval 0.95 to 1.22. Synonymous variants: 57 observed, 62.46 expected, observed/expected ratio (o/e) 0.91, 90% interval 0.74 to 1.14.
Homologues: Orthologues: chimpanzee KRTAP5-6 (93% identical), mouse Krtap5-21 (82% identical), mouse Krtap5-23 (81% identical), mouse Krtap5-25 (77% identical). Paralogues in human: KRTAP5-8 (95% identical), KRTAP5-2 (89% identical), KRTAP5-5 (89% identical), KRTAP4-3 (39% identical), KRTAP4-11 (38% identical), KRTAP4-12 (38% identical), KRTAP4-6 (38% identical), KRTAP10-6 (37% identical), KRTAP10-7 (36% identical), KRTAP4-4 (36% identical), KRTAP4-9 (35% identical), KRTAP10-4 (33% identical), and 35 more.
Diseases named in the same sentence as KRTAP5-6 in open-access papers:
KRTAP5-6 is named in the same sentence as 1 disease in open-access papers, as found by Europe PMC text mining. Sharing a sentence is not in itself a finding about the gene and the disease. The quoted sentences say what the papers report.
diabetes (1 paper, 2021). "The KRTAP5-6 gene encodes a keratin-associated protein as a component of hair matrix, which has not been reported to be related to diabetes." (PMID 34267199, 2021).